STMN1 (stathmin 1)
Diseases named in the same sentence as STMN1 in open-access papers (continued):
Sharing a sentence is not in itself a finding about the gene and the disease.
adrenocortical carcinoma (1 paper, 2022). "Aronova found that STMN1 was overexpressed in adrenocortical carcinoma and promoted a more invasive phenotype in vitro." (PMID 35126478, 2022).
age (1 paper, 2009). A temporal measurement of the time period elapsed since an identifiable point in the life cycle of an organism. "Although stathmin has a significant function in regulating the MT cytoskeleton, surprisingly STMN1 knockout (STMN1-/-) mice develop normally except for some minor age-onset axonopathies associated with STMN1-/- and a lack of learned or innate fear response." (PMID 19643027, 2009).
astrocytoma (1 paper, 2016). "We analyzed MELK and STMN1 expression levels in the series of tissue samples, which included control NN and astrocytoma of all malignant grades." (PMID 26973435, 2016). "MELK and STMN1 expression status was scored according to the median relative expression values (2−ΔCt) of each grade of astrocytoma." (PMID 26973435, 2016). "We detected higher STMN1 expression levels in diffusely infiltrative astrocytomas (AGII to AGIV) compared with AGI." (PMID 26973435, 2016). "STMN1 expression was significantly increased in malignant diffusely infiltrative astrocytomas compared with pilocytic astrocytoma (p < 0.0001)." (PMID 26973435, 2016). "STMN1 gene expression was further assessed in a series of 154 astrocytomas and 22 non-neoplastic brain samples by qRT-PCR." (PMID 26973435, 2016). "Therefore, STMN1 expression was further analyzed simultaneously with MELK gene expression in a series of astrocytomas of different malignant grades and non-neoplastic (NN) brain tissues." (PMID 26973435, 2016). "A significant difference in STMN1 expression levels was also observed among the groups (p < 0.0001), and diffusely infiltrative astrocytomas (AGII to IV) presented higher expression levels than non-invasive pilocytic astrocytomas (AGI) (p < 0.0005, p < 0.0005 and p < 0.05, respectively)." (PMID 26973435, 2016). "The reduced expression of STMN1 in AGI samples compared with NN brain tissue and a stepwise increase that parallels the incremental increase in malignant grade in higher grades of invasive astrocytomas, as shown in the present study, corroborate this suggestion." (PMID 26973435, 2016).
benign prostatic hypertrophy (1 paper, 2022). "The STMN1 expressions were analyzed, immunohistochemically, in formalin-fixed paraffin-embedded 75 PCa and 15 benign prostatic hypertrophy (BPH) tissues." (PMID 37529254, 2022).
Cerebral ischemia (1 paper, 2024). Restriction of arterial blood supply to the brain associated with insufficient oxygenation to support the metabolic requirements of the tissue. "STMN1 is associated with neurons undergoing ectopic chain migration into the ischemic striatum and cerebral cortex following focal cerebral ischemia." (PMID 39062782, 2024).
cholecystolithiasis (1 paper, 2016). Single or multiple, ovoid or irregular, solid particles that are formed from bile, cholesterol, and calcium in the gallbladder cavity. "The expression of miR-223 and STMN1 mRNA in the surgically resected tissue samples from 5 cholecystolithiasis patients and 16 GBC patients, and 2 GBC cell lines was investigated." (PMID 27577078, 2016).
Cutaneous Follicular Lymphoma (1 paper, 2024). A follicular lymphoma involving the skin. "In follicular lymphoma, STMN1 can further serve as a sensitive marker to distinguish primary cutaneous follicular lymphoma from primary cutaneous marginal zone lymphoma." (PMID 38840205, 2024).
dilated cardiomyopathy (1 paper, 2022). Cardiomyopathy which is characterized by dilation and contractile dysfunction of the left and right ventricles. "Besides, we also found that CEBPG was closely related to the ‘Regulation of actin cytoskeleton’ (also enriched in SLC1A4, STMN1 and CBS), ‘Vascular smooth muscle contraction’, ‘Dilated cardiomyopathy’, ‘Relaxin signalling pathway’, ‘Cardiac muscle contraction’ and ‘Hypertrophic cardiomyopathy’." (PMID 35152560, 2022).
endometrial adenocarcinomas (1 paper, 2021). "87% of the endometrial adenocarcinomas stained positively for p16, Stathmin-1, and HSP27." (PMID 34544445, 2021).
esophageal cancer (1 paper, 2021). A primary or metastatic malignant neoplasm involving the esophagus. "We noted that compared to normal tissue, BIRC5, CENPF, STMN1, APOC2, and HNRPC were the five most significantly upregulated genes in esophageal cancer." (PMID 33828156, 2021). "The comparison between esophageal tumors and healthy tissue showed BIRC5 (p = 2.61E−08), APOC2 (p = 3.23E−08), CENPF (p = 4.38E−08), STMN1 (p = 5.74E−08), and HNRPC (p = 8.21E−08) to be five leading genes overexpressed in esophageal cancer." (PMID 33828156, 2021).
esophageal tumors (1 paper, 2021). "The stage-based assessment of overexpressed genes showed significant overexpression of BIRC5, APOC2, CENPF, STMN1, and HNRPC across all cancer stages including early, locally advanced and metastatic esophageal tumors." (PMID 33828156, 2021).
HIV-1 infection (1 paper, 2024). The type species of lentivirus and the etiologic agent of acquired immunodeficiency syndrome (AIDS). "Studies have shown that STMN1, as a microtubule depolymerization protein, affects HIV-1 infection but is involved in HIV-1 transcription." (PMID 38612921, 2024).
Hypercalcemia (1 paper, 2022). An abnormally increased calcium concentration in the blood. "The hypercalcemia GWAS produced a suggestive association (P = 6.81 × 10−7 in LMM, P = 3.05 × 10−7 in FarmCPU) on chromosome C1, located in the gene PAFAH2 (Platelet Activating Factor Acetylhydrolase 2) and within LD of the gene STMN1 (Stathmin 1)." (PMID 35782544, 2022). "The second suggestive association was identified for hypercalcemia and the LD region contained the genes PAFAH2 and STMN1, neither of which have been associated with hypercalcemia previously." (PMID 35782544, 2022).
influenza (1 paper, 2023). An acute viral infection of the respiratory tract, occurring in isolated cases, in epidemics, or in pandemics; it is caused by serologically different strains of viruses (influenzaviruses) designated A, B, and C, has a 3-day incubation period, and usually lasts for 3 to 10 days. "Additionally, genes involved in cell processes and cytoskeletal structural elements were upregulated in activated cTfh cells compared to resting cells following influenza vaccination: ELMO2, ACTG1, STMN1, ANP32B, UCP2, and HMGB3." (PMID 37063867, 2023).
insulinoma (1 paper, 2021). "Studies have found the potential role of STMN1 in regulation of hormone secretion in rodent pituitary and insulinoma cell lines." (PMID 33602139, 2021).
liver failure (1 paper, 2023). A liver disease characterized by the liver losing or has lost all of its function. "The mRNA and protein level of STMN1 increased in CCl4-induced liver failure." (PMID 37514136, 2023). "Therefore, it is quite possible that STMN1 increases in common drug-induced liver failure." (PMID 37514136, 2023).
malignant pleural mesothelioma (1 paper, 2016). A malignant neoplasm that arises from mesothelial cells in the pleura and shows a diffuse growth pattern. "Overexpression of miR-223 was capable to block myeloid cell proliferation through E2F1 inhibition and miR-223 was described as a suppressor of cell proliferation in malignant pleural mesothelioma cells through STMN1 targeting." (PMID 27359057, 2016).
marginal zone lymphoma (1 paper, 2019). A usually indolent mature B-cell lymphoma, arising from the marginal zone of lymphoid tissues. "In addition, we previously demonstrated the diagnostic relevance of STMN1 for FLs including those that are BCL2 negative, and showed its potential usefulness in distinguishing FLs from marginal zone lymphomas (MZLs), which are usually STMN1 negative." (PMID 31686194, 2019).
meningioma (1 paper, 2023). A generally slow growing tumor attached to the dura mater. "Stathmin-1 expression on the other hand is a known marker of PI3K-AKT pathway activation and is increased in AKT1 mutated meningiomas also showing tendency towards beneficial prognosis." (PMID 38023177, 2023).
mesothelioma (1 paper, 2023). A usually malignant and aggressive neoplasm of the mesothelium which is often associated with exposure to asbestos. "The indolyl-chalcones CIT-026 and CIT-223 significantly exert anti-tumor effects against mesothelioma cells by a dual mechanism of action: disruption of microtubule assembly and deregulation of microtubule-associated proteins STMN1 and CRMP2." (PMID 37305581, 2023). "We have investigated the drugs’ mechanisms of action to induce mesothelioma cell death, in particular their impact on microtubule dynamics and microtubule regulators STMN1 and CRMP2." (PMID 37305581, 2023).
metastatic cancer (1 paper, 2025). A carcinoma which has spread from the original site of growth to another anatomic site. "Thus, selectively preventing Stathmin 1 serine 16 phosphorylation may provide an alternative strategy for inhibiting growth factor-mediated metastatic cell growth in combination with current therapies used to eliminate metastatic cancer cells while preventing/inhibiting further metastasis." (PMID 40723207, 2025).
myelofibrosis (1 paper, 2015). A partial or complete replacement of the bone marrow stroma by fibrous tissue. "Notably, Stathmin 1 mRNA levels were highly expressed in CD34+ cells from primary myelofibrosis patients." (PMID 26356819, 2015).
myeloid leukemia (1 paper, 2025). A clonal proliferation of myeloid cells and their precursors in the bone marrow, peripheral blood, and spleen. "For example, it was postulated that STMN1 phosphorylation promoted K562 myeloid leukemia cell proliferation, migration, and invasion since knockdown of PRL-3 mediated these activities." (PMID 40723207, 2025). "Interestingly, the knockdown of phosphatase of regenerating liver-3 (PRL-3) in K562 myeloid leukemia cells decreased total STMN1 expression and increased the phosphorylation of S16, S25, S38, and S63." (PMID 40723207, 2025).
neuroendocrine tumors (1 paper, 2021). "In particular, we describe the usefulness of immunostaining by Stathmin-1, which is a cytosolic phosphoprotein and a key regulator of cell division due to its microtubule depolymerization in a phosphorylation-dependent manner, for the diagnosis of high-grade neuroendocrine tumors." (PMID 34829292, 2021).
ovarian clear cell cancer (1 paper, 2018). An invasive malignant neoplasm that arises from the ovary and is characterized by a predominance of clear and hobnail malignant epithelial cells. "STMN1, which is associated with poor prognosis in GC patients, is regulated by hsa-miR-30a in ovarian papillary serous carcinoma and ovarian clear cell carcinoma." (PMID 29912172, 2018).
polycystic ovary syndrome (1 paper, 2016). A disorder that manifests as multiple cysts on the ovaries. "In this study, we demonstrated that STMN1 is overexpressed in GCs in patients with polycystic ovary syndrome (PCOS)." (PMID 27270953, 2016).
skin papilloma (1 paper, 2012). A benign papillary neoplastic growth on the skin composed of epithelial cells and a fibrous stalk. "Analysis in WT mice revealed that expression of SCG10 was confined to the brain while SCLIP and RB3 were also expressed in thymus and in skin papillomas (at similar levels to stathmin-1)." (PMID 23029098, 2012). "However, based on our results from analysis of skin papillomas, we cannot exclude that SCLIP and RB3 can compensate for the absence of stathmin 1, eventually allowing for tumor onset." (PMID 23029098, 2012).
skin squamous cell carcinoma (1 paper, 2022). A carcinoma arising from the squamous cells of the epidermis. "Li found that overexpression of STMN1 was related to the proliferation, migration, invasion, and apoptosis of human skin squamous cell carcinoma." (PMID 35126478, 2022).
T-cell leukemia (1 paper, 2021). A malignant disease of the T-lymphocytes in the bone marrow, thymus, and/or blood. "Even though TCF7 appeared to be a stronger activator of PU.1 than STMN1, the authors were unable to induce T-cell leukemia in a mouse model by constitutively expressing TCF7-SPI1 on its own9." (PMID 34230493, 2021).
thymoma (1 paper, 2022). A neoplasm arising from the epithelial cells of the thymus. "We also observed that a pre-GC B cell population (STMN1, TCL1A) was preferentially enriched in thymoma." (PMID 35869073, 2022).
tumor (170 papers, 2000 to 2026). "In human CRC specimens, CIC structure formation is associated with low STMN1 expression, poor tumor differentiation, and an inferior prognosis." (PMID 40225568, 2025). "In cancer tissues, STMN1 expression was quantified using Allred scores, revealing a significant association with tumor grade in AdPC." (PMID 39776361, 2025). "Elevated STMN1 expression has been linked to tumor progression and poor prognosis in multiple cancers, including lung, bladder, and liver cancers." (PMID 39776361, 2025). "The LC‒MS/MS results illustrated that HMGA1 is a potential protein that interacts with STMN1 and is significantly associated with tumor metastasis." (PMID 38385074, 2024). "STMN1 is involved in tumorigenesis and tumor progression, with abnormal overexpression linked to aggressive tumor growth and poor prognosis." (PMID 39457014, 2024). "In this study, high levels of STMN1 expression were associated with tumor aggressiveness and poor prognosis in NB, and STMN1 expression was an independent prognostic factor in patients with NB." (PMID 37760452, 2023). "The primary regulator of microtubule dynamics STMN1 is essential for controlling the cell cycle, which is strongly associated with the division and proliferation of tumor cells." (PMID 37509299, 2023). "STMN1 expression was strongly linked with tumor purity (Rho = 0.176, p = 9.98E-04) in the TIMER 2.0 database." (PMID 36127700, 2022). "We observed that high tumor expression of TLR4 was associated with improved overall survival (p = 0.027), whereas low tumor expression of STMN1 was associated with improved overall survival (p < 0.001), both by Kaplan-Meier survival analysis." (PMID 35874727, 2022). "By contrast, GBC instigated an aggressive and immunosuppressive microenvironment, featured by tumor-associated macrophages, Treg cells, CD8+ TEX cells, and STMN1+ tumor-promoting fibroblasts." (PMID 36198671, 2022). "It was shown that the tumor volume and tumor weight significantly decrease in the STMN1 deficiency groups, indicating that the STMN1-knockdown cells obviously lost the capacity of tumor growth in vivo." (PMID 33526768, 2021). "For instance, STMN1 was highly expressed in various tumor cells and was found associated with the clinical manifestations and malignant behavior of tumors." (PMID 34107874, 2021). "Stathmin1 (STMN1), also known as oncoprotein 18, is a phosphorylated protein associated with multiple tumor metastases, which can bind with GRP78 to form STMN1-GRP78 stable complex, mediating tumor metastasis." (PMID 32850882, 2020). "Previous studies of STMN1 expression in solid and hematological malignancies have shown an association with tumor behavior and prognosis." (PMID 31686194, 2019). "Reduction in proliferation and tumor growth by miR-9 at the molecular level was shown to be associated with its targeting of stathmin (STMN1)." (PMID 30813461, 2019). "High expression of STMN1 in tumoral tissue was associated with poor tumor differentiation (P<0.001), lymph node metastasis (P=0.028), advanced TNM stage (P=0.011) and short overall survival (P<0.001)." (PMID 29312550, 2017). "High STMN1 expression in tumor tissue is associated with increased invasion and lymph node metastasis and poor survival." (PMID 29312550, 2017). "(ii) It was reported that Stmn1 plays an oncogenic role and was associated with polyploidy, tumor-cell invasion, early recurrence, and poor prognosis." (PMID 23071542, 2012). "However, in non-tumor cells, STMN1 is considered a telomere-associated senescence marker, and its expression increases in human senescent cells with telomere dysfunction or DNA damage." (PMID 40319242, 2025). "In using the neuronal marker STMN1 as a tumor marker for NB, the possibility of different regulatory mechanisms of STMN1 expression and appropriate cut-off values between low-risk NB and high-risk NB with 1p36 LOH and MYCN amplification should also be considered for risk classification." (PMID 37760452, 2023).